MIR6738 (microRNA 6738)
Synonyms: hsa-mir-6738
Gene: MicroRNA gene on chromosome 1 (155,951,273 to 155,951,336, reverse strand). Ensembl gene ENSG00000277817.
Homologues: Orthologues: chimpanzee MIR6738 (100% identical).